PRMT6 (protein arginine methyltransferase 6)
Diseases named in the same sentence as PRMT6 in open-access papers (continued):
Sharing a sentence is not in itself a finding about the gene and the disease.
glioblastoma (continued). "To elucidate how PRMT6 enhances the invasion of glioblastoma cells, we first analyzed the previously completed proteomic data and found that the protein level of EZH2 was significantly down-regulated in PRMT6-deficient U87 cells." (PMID 39043634, 2024). "Here, we report that PRMT6 functions as a driver element for tumor cell invasion and migration in glioblastoma." (PMID 39043634, 2024). "In experiments involving PRMT6-depleted glioblastoma cells treated with a proteasome inhibitor (MG132), an increase in EZH2 protein expression was observed." (PMID 39043634, 2024). "While PRMT6 has been demonstrated to act as an oncogene in glioblastoma, influencing glioblastoma stem cell division and glioblastoma cell proliferation, its precise regulatory mechanisms in glioblastoma invasion are still not well understood." (PMID 39043634, 2024). "Examination of images depicting the degree of scratch healing revealed that the depletion of PRMT6 expression significantly suppressed the gap closure rate of glioblastoma cells, while PRMT6 overexpression strongly accelerated the gap closure of LN229 cells." (PMID 39043634, 2024). "Western blot and Quantitative Real-Time PCR (qPCR) analyses show that, at both mRNA and protein levels, PRMT6 expression is higher in glioblastoma cell lines compared to normal human brain glial cells (HEB)." (PMID 38637831, 2024). "Our findings demonstrate that PRMT6 is capable of facilitating the post-translational modification of EZH2 in glioblastoma cells." (PMID 39043634, 2024). "Transwell assays revealed that PRMT6 silencing significantly attenuated the invasion of LN229 and U87 cells, while EZH2 overexpression restored the invasive ability of PRMT6-silenced glioblastoma cells." (PMID 39043634, 2024). "We transfected the small interfering RNA targeting TRAF6 into PRMT6-silenced glioblastoma cells to achieve re-inhibition of TRAF6, and subsequently observed an upregulation of EZH2 expression." (PMID 39043634, 2024). "Compared to the PN subtype, MES subtype glioblastomas, which are more aggressive and have poorer prognosis, exhibit significantly higher PRMT6 expression levels." (PMID 38637831, 2024). "Wound healing assay was also conducted to assess the migration effect of PRMT6 on glioblastoma cells." (PMID 39043634, 2024). "Previous research has revealed that in glioblastoma stem cells, PRMT6 methylation of RCC1 controls mitogenesis, tumorigenicity, and radiation sensitivity." (PMID 39528487, 2024). "Our findings illustrate that PRMT6 suppresses TRAF6 transcription via H3R2me2a to enhance the protein stability of EZH2 to facilitate glioblastoma cell invasion and migration." (PMID 39043634, 2024). "Our study demonstrates that PRMT6 acts as an oncogene in glioblastoma, and inhibiting PRMT6 through knockdown or using the inhibitor EPZ020411 notably decreased the invasion and migration of glioblastoma cells." (PMID 39043634, 2024). "PRMT6 has been identified as an oncogene that promotes cell mitosis and proliferation in glioblastoma, highlighting its significance in glioblastoma and suggesting its potential as a therapeutic target." (PMID 39043634, 2024). "Subsequent analysis demonstrates that the invasion of glioblastoma cells in vitro was effectively hampered by a specific PRMT6 small molecule-targeted inhibitor (EPZ020411)." (PMID 39043634, 2024). "The PRMT6 protein levels in the majority of glioblastoma cells (U87, U251, LN229, SNB19) were also higher than that of NHA." (PMID 36792756, 2023). "PRMT6 promotes the tumorigenicity and stem-like properties of the Glioblastoma stem cells (GSCs) by interacting with RCC1 and methylating it at Arg214." (PMID 34575100, 2021). "It was reported that the inhibition of PRMT6 activity by the PRMT6 specific inhibitor EPZ020411 reduces the tumorigenicity of glioblastoma and improves its response to radiotherapy." (PMID 34575100, 2021).
glioblastoma (continued). "Finally, we investigated if the modulation of malignant biological behavior in glioblastoma by PRMT6 and YTHDF2 depends on the activation of the Wnt-β-catenin pathway." (PMID 38637831, 2024). "To determine whether PRMT6 regulates EZH2 protein stability, we measured the abundance of EZH2 in PRMT6-depleted glioblastoma cells and control cells treated with CHX." (PMID 39043634, 2024). "EZH2 has been shown to be regulated by PRMT1, CARM1, and PRMT5, while whether PRMT6 is a regulator of EZH2 in glioblastoma is the subject of further investigation." (PMID 39043634, 2024). "Finally, we further validated the role of the PRMT6-YTHDF2 axis in promoting glioblastoma malignancy in vivo." (PMID 38637831, 2024). "The prognostic significance of PRMT6 expression in patients with MES-subtype glioblastoma was then analyzed, and the results revealed that patients with elevated PRMT6 levels exhibited a poorer overall survival outcome in comparison to those with low PRMT6 expression." (PMID 39043634, 2024). "Previous research has shown PRMT6 enhances glioblastoma cell migration, invasion, and EMT." (PMID 38637831, 2024). "Further investigation into the 100 bp∼−2000 bp region encompassing the TRAF6 promoter in glioblastoma cells demonstrated that PRMT6 and H3R2me2a were significantly enriched at 1400 bp∼1101 bp (F5) and 2000 bp∼1701 bp (F7) upstream of the TRAF6 transcription start site." (PMID 39043634, 2024). "Furthermore, we used EPZ020411 to treat glioblastoma cells for 48 h and obtained similar results, indicating that inhibition of PRMT6 can promote the expression of TRAF6." (PMID 39043634, 2024). "Additionally, rescue experiments demonstrated that PRMT6 enhances glioblastoma cell invasion and migration by modulating TRAF6-mediated EZH2 expression." (PMID 39043634, 2024). "Therefore, further research is necessary to gain a full understanding of the impact of PRMT6 on glioblastoma invasiveness and to provide more comprehensive evidence for targeted therapy in glioblastoma." (PMID 39043634, 2024). "Moreover, in our previous studies, it has been confirmed that PRMT6 silencing in glioblastoma cells significantly inhibits the growth of transplanted tumors and significantly prolongs the survival time of xenograft mice." (PMID 39043634, 2024). "We then explored the prognostic significance of PRMT6 in glioblastoma patients." (PMID 38637831, 2024). "Additionally, our further investigations revealed a notable up-regulation in the transcription of TRAF6 in PRMT6-depleted glioblastoma cells." (PMID 39043634, 2024). "Importantly, our initial experiments demonstrate that a small molecule inhibitor of PRMT6 (EPZ020411) exhibits promising anti-invasive effects on glioblastoma cells in vitro, suggesting the potential for targeted therapy." (PMID 39043634, 2024). "Here, our data confirm that PRMT6 mediates the asymmetric dimethylation of histone H3 at arginine 2 (H3R2me2a) to inhibit the transcription of TRAF6, resulting in a significant decrease in the expression levels of TRAF6 in glioblastoma cells with PRMT6 overexpressing." (PMID 39043634, 2024). "In addition, PRMT6 assists in the maintenance of CSC characteristics in glioblastoma through methylation of the regulator of chromosome condensation 1 (RCC1) protein." (PMID 37394580, 2023). "Xenograft tumor assay and HE staining results showed that the expression of PRMT6 could promote the invasion of glioblastoma cells in vivo, the immunohistochemical staining results of mouse brain tissue tumor sections also confirmed the regulatory relationship between PRMT6, TRAF6, and EZH2." (PMID 39043634, 2024). "Considering that PRMT6 promotes glioblastoma progression and Wnt-β-catenin pathway activation through YTHDF2, and that inhibiting its enzymatic activity reduces YTHDF2 expression, we explored whether this inhibition could suppress malignant phenotypes in glioblastoma." (PMID 38637831, 2024).
glioblastoma (continued). "Therefore, our study demonstrates that PRMT6 could contribute to the proliferation and invasiveness of glioblastoma cells in vivo, which is the main reason why PRMT6 is identified as an oncogene in glioma." (PMID 39043634, 2024). "However, whether PRMT6 increases the invasiveness of glioblastoma cells by promoting the expression of EZH2." (PMID 39043634, 2024). "Therefore, to explore whether PRMT6 has a regulatory effect on EZH2 in glioblastoma cells, we examined the influence of PRMT6 silencing or overexpression on EZH2 expression." (PMID 39043634, 2024). "In glioblastoma, CK2 was reported to phosphorylate and stabilize PRMT6, which enhances the methylation of RCC1, thereby facilitating RCC1 localization in chromatin and contributing to tumorigenicity and progression of glioblastoma." (PMID 39827153, 2025). "To confirm the role of YTHDF2 in PRMT6-induced malignant phenotypes in glioblastoma, we used YTHDF2-overexpressing lentivirus to infect PRMT6-knockdown stable cell lines, creating a double-stable cell model for rescue experiments." (PMID 38637831, 2024). "To investigate the role of EZH2 in PRMT6-mediated glioblastoma cell invasion and migration, we transfected the EZH2 ORF plasmid into PRMT6-silenced glioblastoma cells to re-expressed EZH2 to construct a rescue cell model." (PMID 39043634, 2024). "Then, we identified that PRMT6 maintains the protein stability of EZH2 by inhibiting the degradation of EZH2 protein, thereby mediating the invasion and migration of glioblastoma cells." (PMID 39043634, 2024). "To explore how PRMT6 enhances glioblastoma’s malignant behaviors such as invasion, migration, and EMT, we sought to identify potential downstream targets of PRMT6 in glioblastoma cells." (PMID 38637831, 2024). "Together, these results uncover an essential role of PRMT6 in regulating TRAF6 expression by adding an activating histone methylation mark (H3R2me2a), that is, PRMT6 suppresses the transcription of TRAF6 in glioblastoma cells." (PMID 39043634, 2024). "Furthermore, Western blot results of freshly collected glioblastoma patient protein samples show that PRMT6 protein level expression is significantly higher in glioma, especially in GBM, compared to Normal Brain Tissue (NBT)." (PMID 38637831, 2024). "Analysis of IHC results of 40 samples found that the expression of PRMT6 in glioblastoma was significantly higher than that in LGG, and the expression of PRMT6 in invasive LGG was higher than that in non-invasive LGG." (PMID 39043634, 2024). "Some studies found that PRMT6 methylation of the RCC1 signaling axis regulates mitosis, tumorigenicity, and the radiation response of glioblastoma stem cells." (PMID 34593910, 2021). "Further mechanistic investigations found that PRMT6 inhibits the transcription of TRAF6 by activating the histone methylation mark (H3R2me2a), and reducing the interaction between TRAF6 and EZH2 to enhance the protein stability of EZH2 in glioblastoma cells." (PMID 39043634, 2024). "Hence, EPZ020411, a PRMT6-specific inhibitor, inhibits the methylation of the arginine residue of RCC1 to maximize the positive effects of radiotherapy in a glioblastoma xenograft model." (PMID 37394580, 2023). "The regulatory mark of PRMT6-mediated asymmetric dimethylation of histones is a well-known mechanism that can either activate or repress gene expression, and our previous study demonstrated that PRMT6 can enhance the transcription of CDC20 in glioblastoma cells via H3R2me2a." (PMID 39043634, 2024). "In summary, our research illustrates that PRMT6 acts as an epigenetic regulator, suppressing TRAF6 transcription through histone arginine methylation (H3R2me2a) to inhibit the ubiquitination and degradation of EZH2, thereby promoting invasion and migration of glioblastoma cells." (PMID 39043634, 2024).
glioblastoma (continued). "In addition, glioblastoma cells were treated with a PRMT6 inhibitor (EPZ020411) for 48 h, and it was found that EZH2 protein expression in glioblastoma cells was significantly inhibited, suggesting that PRMT6 may regulate the expression level of EZH2 through post-translational modification." (PMID 39043634, 2024).
prostate carcinoma (9 papers, 2016 to 2025). A carcinoma that arises from epithelial cells of the prostate gland. "In breast and prostate cancer cell lines, PRMT6 has also been associated with reduced apoptosis and the regulation of motility and invasion." (PMID 40461482, 2025). "In contrast, overexpression of PRMT6 was associated with reduced colony formation in breast and prostate cancer cells." (PMID 31428460, 2019). "Ganoderma lucidum polysaccharides have been found to impede cell migration in LNCaP prostate cancer cells via the PRMT6 signaling pathway and promote apoptosis in PC-3 prostate cancer cells, suggesting a preventive role in cancer metastasis." (PMID 40141325, 2025). "The modulation of the PRMT6 signaling pathway emerged as a central mechanism through which GLPs functioned as tumor inhibitors in prostate cancer cells." (PMID 38104078, 2023). "In LNCaP cells, we observed significantly reduced cell proliferation with targeting of either LSD1 or PRMT6, showing that these amiRs exert a biological effect in prostate cancer cells." (PMID 36746939, 2023). "Similar to CRY1 in prostate cancer cells, polyQ-expanded AR bound AREs present in the promoters of Lsd1 and Prmt6 in SBMA myotubes." (PMID 36746939, 2023). "Depletion of PRMT6 in prostate cancer cells promotes apoptosis and decreases the cell migration and invasiveness properties." (PMID 34575100, 2021). "inhibit prostate cancer cell migration through a protein arginine methyltransferase 6 (PRMT6) signaling pathway." (PMID 33807287, 2021). "PRMT6 levels are up-regulated in prostate cancer and in endometrial cancer." (PMID 34575100, 2021). "The binding of pUL69 to PRMT6 could favor oncogenesis as already reported with the upregulated expression of PRMT6 in prostate cancer." (PMID 33937031, 2021). "We verified target silencing in HEK293T cells and in the androgen-sensitive prostate cancer cell line, LNCaP, because LSD1 and PRMT6 are overexpressed in prostate cancer and correlate with cancer aggressiveness 22,23,27." (PMID 36746939, 2023). "The multifaceted approach exhibited by GLPs, involving the inhibition of PRMT6 signaling and the activation of NAG-1, combined with the regulation of Akt and MAPK/ERK pathways, underscores their potential as a valuable agent in combating prostate cancer." (PMID 38104078, 2023).
colon cancer (8 papers, 2018 to 2024). "Loss of PPAR-α enhances colon carcinogenesis, indicated by increases in DNA methyltransferase 1 (DNMT1) and protein arginine methyltransferase 6 (PRMT6) in colon tumors from PPAR-α-deficient mice." (PMID 39494346, 2024). "However, among the PRMTs tested, only PRMT6 showed a significant association with disease-free survival, indicating that enzyme expression is a useful indicator of unfavorable prognosis for colon cancer." (PMID 29507670, 2018). "The loss of PPARα in the intestines has been proposed to increase DNMT1 (methyltransferase 1)-mediated p21 methylation and PRMT6 (protein arginine methyltransferase 6)-mediated p27 methylation, thereby promoting the development of colon cancer." (PMID 37305395, 2023). "PRMT6 is dramatically elevated in a variety of human malignancies, including lung, breast, prostate, and colon cancer, implying an important role for PRMT6 in tumors." (PMID 36792756, 2023). "PRMT6 levels are elevated in colon cancer possibly due to the hypomethylation of PRMT6 promoter regions." (PMID 34575100, 2021). "PPARα regulates the expression of DNMT1 and PRMT6 in the intestinal cells and protects against colon cancer." (PMID 34575100, 2021). "An abundance of PRMT6 is correlated with the shorter disease-free survival of colon cancer patients." (PMID 34575100, 2021). "Besides interactions of PPARα and TET enzymes in early development, associations of PPARα inhibition with the increased expression of DNA methyltransferase I (DNMT1) and protein arginine methyltransferase 6 (PRMT6) have already been demonstrated in colon cancer and the liver." (PMID 36551797, 2022).
emphysema (6 papers, 2020 to 2024). "To examine whether the emphysema-protective effect of PRMT6 was associated with an anti-inflammatory effect on the mice after CSE injection, we measured the levels of TNFα and IL-1β in the lung tissues." (PMID 32047419, 2020). "In a mouse model of CSE-induced emphysema, a lentivirus-mediated overexpression of PRMT6 can improve lung function." (PMID 39206196, 2024). "Our previous work proved that PRMT6 overexpression in the respiratory system alleviated the emphysema change in a cigarette smoke extract intraperitoneal-established COPD mouse model." (PMID 33959602, 2021). "Consistent with the results of IHC, immunoblotting results verified the reduced expression of PRMT6 in CSE-induced emphysema lung tissue homogenates." (PMID 33260152, 2020). "Our data indicate that the activation of NF-κB was negatively regulated by PRMT6 in the emphysema model, which was probably induced by tri-methylation of H3K4." (PMID 32047419, 2020). "Given the substantial low expression of PRMT6 in CSE-induced emphysema mouse lung tissues, we evaluated the expression of PRMT6 in human bronchial epithelial cells." (PMID 33260152, 2020). "In all, these results indicate that intraperitoneal injection of CSE successfully induced lung emphysema and PRMT6 protein was downregulated in CSE-induced emphysema mouse lung tissues." (PMID 33260152, 2020). "To explore the role of PRMT6 in cigarette smoke mediated emphysema, we first established an experimental mouse emphysema model by intraperitoneal injection of CSE." (PMID 33260152, 2020). "PRMT6 also plays a protective role in CSE-induced emphysema." (PMID 39206196, 2024). "Moreover, ectopic PRMT6 expression in the lung alleviated emphysema morphology change in a CSE-established mouse model." (PMID 33959602, 2021). "Overexpressed protein arginine methyltransferase-6 may suppress the ability of cigarette smoke extract to activate NF-κB and induce pro-inflammatory gene expression in a murine emphysema model." (PMID 33535173, 2021). "The overexpressed PRMT6 could serve as an inflammation inhibitor, potentially through blocking the NF-κB/p65 pathway in the murine emphysema model." (PMID 32047419, 2020). "It is surprising to observe that the overexpressed PRMT6 could serve as an inflammation inhibitor by blocking the NF-κB/p65 pathway in the murine emphysema model." (PMID 32047419, 2020). "A histone methyl modifier, protein arginine N-methyltransferase 6 (PRMT6), is reported to alleviate cigarette smoke extract (CSE)-induced emphysema through inhibiting inflammation and cell apoptosis." (PMID 33959602, 2021). "The present study confirmed the findings that PRMT6, an essential epigenetic enzyme, contributed to the beneficial effects on CSE-induced murine emphysema." (PMID 32047419, 2020). "In the present study, we examined whether PRMT6 could attenuate the inflammation of COPD and investigated the relationship between PRMT6 and NF-κB signaling pathway in a CSE-induced murine emphysema model." (PMID 32047419, 2020).